CCL5 (C-C motif chemokine ligand 5)
Diseases named in the same sentence as CCL5 in open-access papers (continued):
Sharing a sentence is not in itself a finding about the gene and the disease.
rheumatic disease (2 papers, 2009 to 2021). "Hepatocyte growth factor was significantly increased in the group of rheumatic diseases patients (SSc+ORD) compared with HC, while chemokine (C-C motif) ligand 5 (CCL5) was significantly higher in SSc patients compared with ORD and HC." (PMID 33313931, 2021).
rhinitis (2 papers, 2010 to 2014). An inflammation of the mucous membrane lining the nose, usually associated with nasal discharge. "Nasal mucosal biopsies from seasonal rhinitis patients were found to contain elevated CCL5/RANTES+ eosinophils, making up around 15% of the total CCL5/RANTES+ population of cells." (PMID 25426119, 2014).
Salmonella Infections (2 papers, 2019 to 2023). Infections with bacteria of the genus SALMONELLA. "Salmonella infection triggers the secretion of CCL5 by macrophages as expected, but the level of secretion increases when infecting with an ΔsrfJ mutant, suggesting that SrfJ contributes to the modulate secretion of this chemokine." (PMID 37176110, 2023).
sarcopenia (2 papers, 2024 to 2025). Progressive decline in muscle mass due to aging which results in decreased functional capacity of muscles. "In the same way as CCL5, other myokines have been shown to activate molecular mechanisms involved in sarcopenia." (PMID 39857418, 2025). "To evaluate possible muscular alterations related to sarcopenia due to the overexpression of CCL5, we first assessed the diameter of muscle fibers in the TA muscles after 7 and 21 days of electroporation." (PMID 39857418, 2025). "In summary, our work establishes, for the first time, that CCL5 is a myokine that induces sarcopenia in vivo." (PMID 39857418, 2025). "Upon confirming that the overexpression of CCL5 can induce sarcopenia in skeletal muscle, we analyzed the ccr5 and ccr1 gene expression." (PMID 39857418, 2025). "Our research demonstrates that the overexpression of CCL5 in the tibialis anterior (TA) muscle induces sarcopenia, reducing muscle mass and strength." (PMID 39857418, 2025). "Our findings demonstrate that the overexpression of CCL5 in TA induces sarcopenia 21 days after electroporation, decreasing muscle mass and the ability to generate force in the TA muscle." (PMID 39857418, 2025). "The results showed that TA overexpression of CCL5 led to sarcopenia by reducing muscle strength and mass, muscle-fiber diameter, and sarcomeric protein content, and by upregulating E3-ligases." (PMID 39857418, 2025). "Furthermore, we show that ccl5 mRNA levels increase in skeletal muscle in a model of sarcopenia due to cholestatic liver disease and induce some alterations in sarcomeric proteins related to UPS." (PMID 39857418, 2025). "The present study establishes that CCL5 overexpression in skeletal muscle can induce sarcopenia." (PMID 39857418, 2025). "However, future studies to analyze the influence of CCL5 on some processes that regulate mitochondrial homeostasis—specifically, alterations in mitochondrial biogenesis, dynamics, or mitophagy, which have been previously shown to be altered in several conditions of sarcopenia —could be conducted." (PMID 39857418, 2025).
Splenomegaly (2 papers, 2013 to 2018). Abnormal increased size of the spleen. "Ltr7 controls splenomegaly (in interaction with Ltr5) and in interaction with Ltr3 level of both CCL3 and CCL5 in serum." (PMID 23875032, 2013).
tongue tumor (2 papers, 2021 to 2024). "Therefore, we further validated the expression of Th1-associated chemokine genes, including Cxcl9, Cxcl10, and Ccl5, and Th2/Treg-associated chemokine genes, including Ccl17 and Ccl22, in carcinogen-induced tongue tumors using qRT-PCR." (PMID 33921389, 2021). "Furthermore, CCL5 protein expression levels were confirmed in Pa and LM4 tongue tumor tissues using ELISA." (PMID 39126553, 2024).
urticaria (2 papers, 2017 to 2022). A vascular reaction of the skin characterized by erythema and wheal formation due to localized increase of vascular permeability. "For example, CCL5/RANTES, CCL2/MCP-1, and CXCL8/IL-8 are able to induce histamine and serotonin release by mast cells, suggesting their contribution to the development of urticaria by a direct effect on mast cell degranulation." (PMID 29038618, 2017).
visceral leishmaniasis (2 papers, 2012 to 2023). A severe form of leishmaniasis characterized by irregular bouts of fever, substantial weight loss, swelling of the spleen and liver, and anemia (which may be serious). "Validation of our DP cohort results revealed that CXCL10, but not CCL2, CCL5 or CXCL8 transcripts, were significantly upregulated by Leishmania infantum infection with or without clinically definite visceral leishmaniasis." (PMID 37601355, 2023).
vivax malaria (2 papers, 2013 to 2017). "In the present study, vivax malaria patients have shown significant low RANTES/CCL5 levels, but just weakly associated with IL-6, IL-12p40, IFN-γ or MCP-1/CCL2." (PMID 28118834, 2017). "In the present study and not surprisingly, IFN-γ and TNF and the chemokine CCL5 were demonstrated to be crucial biomarkers in the network profile of those individuals with mild vivax malaria." (PMID 23433077, 2013).
Acidosis (1 paper, 2025). Abnormal acid accumulation or depletion of base. "Acidosis-induced RASF elevates the transcription levels of numerous cytokines, encompassing classical innate immune cell chemotactic combinations such as CCL2, IL8, and CCL5, along with inflammatory cytokine combinations like IL6 and IL12, which are contingent upon adaptive immune responses." (PMID 40234753, 2025).
Acute hepatitis (1 paper, 2016). Acute hepatic injury resulting from inflammation typically accompanied by increased serum alanine transaminase activity. "In a model of Concanavalin A-induced acute hepatitis, the treatment of CCR5-/- mice with a monoclonal anti-CCL5 antibody led to markedly reduced hepatocyte damage and a significant reduction in NK cells in the liver parenchyma." (PMID 27977747, 2016).
acute leukemia (1 paper, 2017). A clonal (malignant) hematopoietic disorder with an acute onset, affecting the bone marrow and the peripheral blood. "Serum samples from CRMO patients contained higher concentrations of CCL4/MIP-1β, CCL5/RANTES, CCL11/eotaxin, S100A8, and lower concentrations of IL-18, sIL-2R, and osteoprotegerin when compared to samples from patients with acute leukemia." (PMID 29250517, 2017).
acute respiratory failure (1 paper, 2023). Life-threatening respiratory failure that develops rapidly. "CCL5/RANTES has been associated with severity of lung damage in ARDS, a clinical syndrome of severe acute respiratory failure, and is an independent risk factor for development of acute lung injury." (PMID 37788115, 2023).
age (1 paper, 2026). A temporal measurement of the time period elapsed since an identifiable point in the life cycle of an organism. "Collectively, these results indicate that Hevin plays a role in the advancement of age‐related cardiac dysfunction, partly by triggering the induction of CCL5." (PMID 41521391, 2026). "In essence, our discoveries demonstrate that Hevin fosters age‐related cardiac dysfunction by activating cardiac macrophages via TLR4, prompting their polarization and CCL5 release." (PMID 41521391, 2026).
amyloidoma (1 paper, 2024). Nodular localized form of amyloidosis with predominantly thoracic localization (pulmonary amyloidosis), considered as secondary protein structure disease in which insoluble protein fibrils accumulate extracellularly. "ALλ(CLA) amyloidomas contained significantly more CXCL10, GM-CSF (granulocyte monocyte-colony stimulating factor), and IL-10, with more expression of CCL5 trending towards significance (p=0.0882)." (PMID 39600710, 2024).
anthrax (1 paper, 2015). "Elevated transcription of TNF-α, IL-1α, IL-1β, IL-4, IL-6, CCL5, CXCL2 and KC have been observed in both murine anthrax challenge models and in vitro macrophages and monocytic cell lines exposed to anthrax antigens." (PMID 26075052, 2015).
aortic atherosclerosis (1 paper, 2013). A atherosclerosis that involves the aorta. "Likewise, reduced total cholesterol and HDL levels, as well as increased low-density lipoprotein (LDL)/vLDL, IL-6, sRANKL and CCL5 circulating levels mirroring RA patients was observed in the K/BxAg7 mice, a novel animal model of erosive arthritis followed by prominent aortic atherosclerosis." (PMID 23941259, 2013).
Aphasia (1 paper, 2023). An acquired language impairment of some or all of the abilities to produce or comprehend speech and to read or write. "The need to express informed consent for additional blood sampling for CCL5 determination resulted in the exclusion of patients with impaired consciousness or aphasia." (PMID 37759440, 2023).
arenavirus infection (1 paper, 2013). "Thus, comparison of our study with LCMV infection model suggests that arenavirus infection can lead to highly similar transcriptional fingerprints, which have a few notable differences in differing kinetics of interferon induction and expression of CCL5 and CREB1." (PMID 23638192, 2013).
aspergillosis (1 paper, 2020). Aspergillosis is an infection, growth, or allergic response caused by the Aspergillus fungus. "The chemokines (CCL3, CCL2, and CCL5) followed in this study have been previously shown to be associated with aspergillosis since they are involved in the recruitment of neutrophils, platelets, and monocytes, but the molecules responsible for the chemokine production have not been identified." (PMID 31915215, 2020).
autoimmune encephalitis (1 paper, 2023). Inflammation of the brain secondary to an immune response triggered by the body itself. "In order to show the activation of the bone marrow via the CCL5(Rantes)-CCR5 axis, which has been previously implied as a major pathway activating bone marrow by T-lymphocytes during autoimmune encephalitis, we performed an ELISA for CCL5." (PMID 37810891, 2023).
B-cell lymphoma (1 paper, 2021). "Monocytes, which could be recruited by large B-cell lymphoma cells via leukocyte attractant CCL5, can promote tumor cell survival and proliferation." (PMID 33996552, 2021).
Behcet disease (1 paper, 2017). A chronic, relapsing, multisystemic vasculitis characterized by mucocutaneous lesions, as well as articular, vascular, ocular and central nervous system manifestations. "Our study confirms earlier data presenting the absence of an association between the chemokine genes rs1024610/CCL2 and rs2280788/rs2107538/CCL5 with Behcet's disease or retinal vasculitis in patients from UK." (PMID 28589131, 2017).
benign breast disease (1 paper, 2022). "Additionally, CCL5 is highly expressed in advanced triple‐negative breast cancer, whereas CCL5 is not overexpressed in breast tissue from women with benign breast disease or those who have undergone breast reduction." (PMID 35702353, 2022).
celiac disease (1 paper, 2024). An autoimmune genetic disorder with an unknown pattern of inheritance that primarily affects the digestive tract. "CCL5 gene expression was also upregulated in duodenal biopsies obtained from a cohort of Pakistani patients with EED compared to healthy US controls or patients with celiac disease." (PMID 38589975, 2024).
chronic asthma (1 paper, 2020). An asthma that is characterized by the development of persistent airway inflammation and recurrent attacks of breathlessness and wheezing, which vary in severity and frequency. "This study aimed to evaluate plasma CCL5 (chemokine) and IL-5 (cytokine) as well as eosinophils in peripheral blood and sputum and their possible role in patients with chronic asthma who visited emergency rooms during sandstorms." (PMID 32467785, 2020). "This study aimed to evaluate the usefulness of C-C chemokine ligand 5 (CCL5) chemokine and interleukin 5 (IL-5) cytokine and determine the total eosinophil count in blood and sputum for use as biomarkers in Saudi patients with chronic asthma who visited emergency departments during sandstorms." (PMID 32467785, 2020).
cicatricial alopecia (1 paper, 2025). Scarring hair loss, also known as cicatricial alopecia, is the loss of hair which is accompanied with scarring. "A phase 2a study evaluating the efficacy of oral dual JAK1/tyrosine kinase 2 inhibitor brepocitinib in cicatricial alopecias found significant downregulation of inflammatory biomarkers, including CCL5, and demonstrated a favorable safety profile." (PMID 40778340, 2025).
Cm (1 paper, 2025). "Collectively, these results indicate that NK cell depletion reduces CCR5, CCL3, and CCL5 levels, consequently impairing DC recruitment and migration during Cm infection." (PMID 40332391, 2025).
cocaine addiction (1 paper, 2023). "One chemokine receptor system involved in the pathophysiology of cocaine addiction is CCR5, whose ligands are CCL3 and CCL5." (PMID 36830990, 2023).
Cough (1 paper, 2017). A sudden, audible expulsion of air from the lungs through a partially closed glottis, preceded by inhalation. "Poly(I:C), as expected, up-regulated genes associated with inflammation, innate immunity and viral responses including CXCL11, CCL5 (chemokine (C–C motif) ligand) 5 and CXCL10, interferon-induced protein 44 like (IFI44L) in ASMCs from both healthy non-cough and chronic cough volunteers." (PMID 28842514, 2017).
Cryptococcal meningitis (1 paper, 2014). Meningeal inflammation produced by cryptococcus neoformans, an encapsulated yeast that tends to infect individuals with acquired immunodeficiency syndrome and other immunocompromised states. "In addition, increased CSF levels of CCL5 have been identified in HIV+ patients with some opportunistic infections of the CNS (i.e. cryptococcal meningitis) when compared with CSF levels of HIV-infected patients without the opportunistic infection." (PMID 24658403, 2014).
dermopathy (1 paper, 2023). "EGFR inhibitors induce C–C motif chemokine ligand 5 (CCL5) in dermopathy." (PMID 38092882, 2023).
diabetic eye disease (1 paper, 2024). A group of disorders affecting the eye in patients with diabetes mellitus. "However, concentrations of chemokines (CCL3, CCL9 and CXCL1) retained no significance alone and concentrations of chemokines (CCL5 and CXCL4) were lower in the diabetic eye disease patients than in the controls." (PMID 38790059, 2024).
diabetic neuropathy (1 paper, 2024). A chronic, pathological complication associated with diabetes mellitus, where nerve damages are incurred due to diabetic microvascular injury involving small blood vessels that supply these nerves, resulting in peripheral and/or autonomic nerve dysfunction. "Additionally, it has been shown that CCR5, CCL2, CCL3, CCL5, CCL7, CCL8, and CCL12 spinal mRNA and/or protein levels are elevated in rodent models of diabetic neuropathy, with some displaying sex-related diversity." (PMID 39457105, 2024).
diarrhoea (1 paper, 2022). "Other DEGs that were down-regulated in the high-diarrhoea group include Ovar-DRB1, DQA, TREM2, TFF3, ITLN2, CD74, CCL5, and CCR3." (PMID 35140270, 2022).
erysipelas (1 paper, 2017). An infection of the upper layers of the skin caused by species of streptococcus. "Our observation linked the high levels of expressed CCL5 in erysipelas patients who were linked to the homozygous T genotype in SOD2 C2734T SNP." (PMID 28512644, 2017).
Erythema (1 paper, 2023). Redness of the skin, caused by hyperemia of the capillaries in the lower layers of the skin. "In addition, PPD induration was found to significantly increase the levels of the inflammatory factor IL-6 and the chemokine CCL5 compared to EC erythema." (PMID 38068935, 2023). "The expression of CCL5 in PPD induration was reported to be significantly higher than in EC erythema, which could increase CD4+ and CD8+ T infiltration, consistently with our immunohistochemical results." (PMID 38068935, 2023). "At the same time, the inflammatory factors IL-6 and chemokine CCL5 were both detected, and it was noted that they were upregulated in both PPD induration and EC erythema compared to the control and that their levels were significantly higher in the PPD induration group than in the EC erythema group." (PMID 38068935, 2023).
esophageal tumor (1 paper, 2025). "Another study demonstrated that an 8-hydroxyquinoline derivative effectively suppresses esophageal tumor invasion by downregulating CCL5 expression, suggesting that CCL5 may serve as a potential therapeutic target for inhibiting tumor progression." (PMID 40396123, 2025).
Glanzmann thrombasthenia (1 paper, 2021). "This difference in CCL5 and CXCL4 release was also observed in platelets isolated from two patients with Glanzmann thrombasthenia, who have defective αIIbβ3integrins." (PMID 34901735, 2021).
Hashimoto thyroiditis (1 paper, 2023). An autoimmune disorder caused by the production of autoantibodies against thyroid tissue. "In the Hashimoto’s thyroiditis (HT), one study has proved that CCL5/ACKR1 axis facilitated the trans-endothelial migration of lymphocytes." (PMID 37207221, 2023).
hearing loss (1 paper, 2019). "As a TF, FOS may participate in inflammation by regulating its target genes, such as ICAM-1, CSF1 and CCL5 which were all important inflammatory proteins for hearing loss." (PMID 31149396, 2019).
herpangina (1 paper, 2021). "EV-A71 infection induced interferon, pro-inflammatory cytokines and chemokines, including IFN-β, IL-6, CCL5, and TNF-α in tonsillar epithelial cells, which may play a critical role in EV-A71-caused herpangina." (PMID 33481814, 2021).
HIV-associated neurocognitive disorder (1 paper, 2024). HIV-associated neurocognitive disorder (HAND) remains a common complication of HIV infection in the combination antiretroviral therapy (ART) era. "Abundant CCL5 has been associated with many inflammatory disorders, cancers, and HIV-associated neurocognitive disorder (HAND)." (PMID 39609320, 2024).
Hydrocephalus (1 paper, 2025). Hydrocephalus is an active distension of the ventricular system of the brain resulting from inadequate passage of CSF from its point of production within the cerebral ventricles to its point of absorption into the systemic circulation. "Studies report that C-C motif chemokine ligand 5 (CCL5) mediates leukocyte infiltration into the ventricular system, triggering inflammatory responses that disrupt CSF circulation and induce hydrocephalus." (PMID 40672443, 2025).
hydronephrosis (1 paper, 2014). Collection of urine in the renal pelvis that results in dilatation of the renal pelvis and calyces. "In this regard, chemokines like CCL2/MCP-1, CCL5/RANTES, macrophage inflammatory protein-2 (CXCL2/MIP-2), and γ-interferon-inducible protein (CXCL10/IP-10) have been evaluated in experimental hydronephrosis." (PMID 24692841, 2014).
Hypofibrinogenemia (1 paper, 2020). Decreased concentration of fibrinogen in the blood. "The increase in CCL-5 levels in patients who presented hypofibrinogenemia may be associated with a possible action of the generated thrombin and FXa, since these factors are responsible for the expression of this chemokine in fibroblasts, platelets, and endothelial cells." (PMID 32973773, 2020).
ileitis (1 paper, 2024). "In addition, SHIP-1−/− mice exhibited increases in serum IL-12(p40) and CXCL1, and a reduction in IL-12(p70) and CCL5 that were independent of ileitis development." (PMID 39432107, 2024).
immunodeficient diseases (1 paper, 2022). "The functional capacities of the highly expressed DEGs in the Chinese Simmental cattle mainly focused on inflammatory diseases (CXCL9 and FCRL1), immunodeficient diseases (ADM2, CCL5, and CAMKV), carcinoma (CXCL11, JAKMIP2, GZM, and DNAAF1), and GTP binding and GTPase activity (NUGGC)." (PMID 35495650, 2022).
interstitial cystitis (1 paper, 2022). A rare chronic debilitating urogenital disease characterized by urinary frequency, urgency, and pelvic pain. "Ccl5 gene, also found to be upregulated in the SC in CIE 1 wk group, was detected at increased levels in the urine of interstitial cystitis patients and was associated with voiding dysfunction in these patients." (PMID 36490282, 2022).